HCAR2 (hydroxycarboxylic acid receptor 2)
Diseases named in the same sentence as HCAR2 in open-access papers (continued):
Sharing a sentence is not in itself a finding about the gene and the disease.
skin cancer (3 papers, 2011 to 2020). "It was early observed that the expression of HCAR2 was diminished in several human cancers such as colon, compared with the paired colon tissue and primary breast tumor tissues; in addition, an impaired functionality of HCAR2 was associated with skin cancer." (PMID 33113952, 2020). "In a similar manner to that reported for HCAR2, the functionality of HCAR3 seems to be impaired in skin cancer, but little is known about its relevance in tumor processes." (PMID 33113952, 2020).
viral infection (3 papers, 2019 to 2025). "The result showed that even at an MOI of 0.5, HCAR2 mRNA level was also enhanced by viral infection (~2.6-fold at 24 h p.i.)." (PMID 32039055, 2019).
osteoarthritis (2 papers, 2024 to 2025). A noninflammatory degenerative joint disease occurring chiefly in older persons, characterized by degeneration of the articular cartilage, hypertrophy of bone at the margins and changes in the synovial membrane. "β-Hydroxybutyrate enhances chondrocyte mitophagy and reduces cartilage degeneration in osteoarthritis via the HCAR2/AMPK/PINK1/Parkin pathway, and it alleviates cartilage senescence through the hnRNP A1-mediated upregulation of PTEN." (PMID 40027098, 2025).
Stroke (2 papers, 2015 to 2021). Sudden impairment of blood flow to a part of the brain due to occlusion or rupture of an artery to the brain. "Interestingly in the context of our present study, HCAR2 activation in bone marrow-derived inflammatory macrophages that infiltrate the brain in a mouse model of stroke induces a neuroprotective phenotype in these cells." (PMID 25920452, 2015).
acute kidney injury (1 paper, 2023). Sudden and sustained deterioration of the kidney function characterized by decreased glomerular filtration rate, increased serum creatinine or oliguria. "Moreover, HCAR2 is also expressed by murine renal tubular epithelial cells in the context of sepsis-associated acute kidney injury (AKI)." (PMID 37814337, 2023).
age (1 paper, 2025). A temporal measurement of the time period elapsed since an identifiable point in the life cycle of an organism. "To investigate the potential mechanisms through which aerobic exercise delays age-related sarcopenia, we explored the regulation of the β-HB/HCAR2–PPARG signaling pathway." (PMID 40710572, 2025).
amyloid (1 paper, 2025). "Hydroxycarboxylic acid receptor 2 (HCAR2), a niacin receptor expressed in microglia, is markedly induced by amyloid pathology in AD." (PMID 40640892, 2025).
dyslipidaemias (1 paper, 2019). "Nicotinic acid (NA) activates hydroxycarboxylic acid receptor 2 (HCA2), and it is widely used in treating dyslipidaemias." (PMID 31273921, 2019).
glaucoma (1 paper, 2018). Increased pressure in the eyeball due to obstruction of the outflow of aqueous humor. "We detected significantly increased mRNA and protein levels of HCAR1 but not HCAR2 in D2 retina and ON, indicating that ketogenic diet treatment induces HCAR1 expression in glaucoma mice." (PMID 30424795, 2018).
hematoma (1 paper, 2025). A hematoma is a collection of blood from a vascular structure into an extravascular space. "Collectively, these findings suggest that niacin may facilitate microglial M2 polarization and enhance phagocytic activity through an HCAR2-dependent mechanism, thereby accelerating hematoma clearance after GMH." (PMID 41205412, 2025). "Through HCAR2-dependent regulation of the CD36/CD163/HO-1 axis, niacin enhances M2 microglial phagocytosis, accelerates hematoma clearance, reduces hydrocephalus, and improves neurological outcomes while mitigating neuroinflammation and oxidative stress." (PMID 41205412, 2025).
Hydrocephalus (1 paper, 2025). Hydrocephalus is an active distension of the ventricular system of the brain resulting from inadequate passage of CSF from its point of production within the cerebral ventricles to its point of absorption into the systemic circulation. "Collectively, niacin regulates microglial function via the HCAR2/SIRT1/Nrf2 signaling axis to reduce neuronal damage, neuroinflammation, and oxidative stress, thereby alleviating hydrocephalus and improving neurological outcomes." (PMID 41205412, 2025).
hyperandrogenemia (1 paper, 2019). "Furthermore, HCAR2 (hydroxycarboxylic acid receptor 2) was significantly upregulated in both T and T + WSD groups, suggesting a WSD-independent effect of hyperandrogenemia." (PMID 31848372, 2019).
knee osteoarthritis (1 paper, 2021). "Deficiency of the HCAR2 agonist niacin (vitamin B3) was associated with knee osteoarthritis progression in the Japanese ROAD cohort." (PMID 34450027, 2021).
liver cancer (1 paper, 2025). An epithelial or non-epithelial malignant neoplasm that arises from the liver. "In liver cancer, the blockage of glutamine uptake eliminates hydroxycarboxylic acid receptor 2, also known as GPR109A, and niacin receptor 1 (NIACR1) suppressive effect on myeloid cells." (PMID 40361394, 2025).
liver fibrosis (1 paper, 2021). "Niacon, an HCAR2 agonist, has shown anti-fibrotic properties against liver fibrosis in rats." (PMID 34830489, 2021).
melanoma (1 paper, 2020). A malignant, usually aggressive tumor composed of atypical, neoplastic melanocytes. "Finally, we show for the first time that the expression levels of Niacin receptors HCAR2 and HCAR3 is almost abolished in human melanoma samples." (PMID 33028392, 2020). "GEPIA2 analysis indicated a strong reduction of HCAR2 and HCAR3 expression in melanoma patients as compared to normal skin controls." (PMID 33028392, 2020).
myocardial infarction (1 paper, 2025). Gross necrosis of the myocardium, as a result of interruption of the blood supply to the area, as in coronary thrombosis. "We investigated whether MMF can attenuate myocardial infarction (MI) injury and delineated the underlying mechanisms, focusing on hydroxycarboxylic acid receptor 2 (HCAR2, also known as GPR109A) and PI3K/Akt signaling." (PMID 41469385, 2025).
ZIKV infection (1 paper, 2019). "Firstly, the data obtained with mRNA microarray and qRT-PCR assays showed that the expression of HCAR2 was significantly induced by ZIKV infection, indicating a strong association between HCAR2 and ZIKV life cycle." (PMID 32039055, 2019). "In our study, we demonstrated that the IRE1-XBP1 pathway mediates the induction of HCAR2 upon ZIKV infection." (PMID 32039055, 2019). "Our study compared the HCAR2 mRNA levels in the context of ZIKV infection with treatment of IRE1 inhibitors or XBP1-specific shRNAs." (PMID 32039055, 2019). "Furthermore, the expression level of HCAR2 in response to a lower MOI of ZIKV infection (MOI 0.5) was also examined." (PMID 32039055, 2019). "In order to identify more novel host factors, we screened ZIKV-related genes through mRNA microarray and found that the expression of hydroxycarboxylic acid receptor 2 (HCAR2) could be dramatically induced by ZIKV infection." (PMID 32039055, 2019). "Similarly, the expression of HCAR2 in SNB19 cells was also increased in response to ZIKV infection in a time-dependent manner (~5-fold at 12 h p.i., ~13-fold at 24 h p.i., and ~29-fold at 48 h p.i.)." (PMID 32039055, 2019). "To identify host factors contributing to ZIKV pathogenesis, transcriptomic landscape in ZIKV-infected cells was examined with mRNA microarray analysis and we observed that the expression of hydroxycarboxylic acid receptor 2 (HCAR2) could be significantly induced by ZIKV infection." (PMID 32039055, 2019). "Taken together, our work provides the first evidence to show a relationship between host HCAR2 and virus: the expression of HCAR2 could be significantly up-regulated by ZIKV infection through the IRE1-XBP1 pathway, and in turn, HCAR2 reduces the ZIKV replication." (PMID 32039055, 2019). "Moreover, the mRNA level of HCAR2 was not increased by ZIKV infection with GSK2850163 or 4μ8c treatment." (PMID 32039055, 2019). "The top 50 genes up-regulated by ZIKV infection were shown, but HCAR2 gene was not in the list." (PMID 32039055, 2019). "Similarly, the mRNA level of HCAR2 in XBP1-KD cells was not enhanced in response to ZIKV infection." (PMID 32039055, 2019).
tumor (40 papers, 2011 to 2025). "HCAR2, the nicotinic acid receptor, has recently been reported to have BC tumor suppressing properties; thus, rare, non-synonymous variants in HCAR2 likely disrupt protein function, increasing BC susceptibility." (PMID 34852802, 2021). "Through activation of HCAR2 (hydroxycarboxylic acid receptor 2), it suppressed NF-κB signaling, reducing inflammation and enhancing anti-tumor immune responses." (PMID 41375220, 2025). "Intriguingly, however, the effects of HCAR1 and HCAR2 on tumor growth are diametrically opposed: HCAR1 is a tumor promoter, while HCAR2 is a tumor suppressor." (PMID 40233099, 2025). "There were two macrophage subgroups that mainly existed in the Sephin1 group: Chil3+ macrophages, which mainly existed in the day 15 blood samples, and Hcar2+ macrophages, which mainly existed in day 15 tumor samples." (PMID 36718369, 2023). "Except for two subtypes with too few cells (Retnla+ macrophages and Hcar2+ macrophages), we found that the subtypes mainly existing in tumor tissues were more tended to M2 polarization, including the Spp1+, Clqb+, Ifitm6+, and Facn1+ macrophages." (PMID 36718369, 2023). "These variants were exclusively identified in HCAR1 and HCAR3, which is notable considering their suggested oncogenic role and requirement for BC proliferation/survival compared to the demonstrated tumor suppressor properties of HCAR2." (PMID 34852802, 2021). "For instance, HCAR2 is described as a tumor suppressor gene because it exhibits a 70% reduction of cell-surface expression in primary BC cells; and its cellular expression is essential for the initiation of apoptosis by its endogenous ligands." (PMID 34852802, 2021). "The ketone body β-hydroxybutyrate (BHB) can replicate the tumor-suppressing effect of the ketogenic diet through surface receptor Hcar2 and transcriptional regulator Hopx, suggesting that the tumor-inhibitory effect of diet can be replicated by supplementing metabolites." (PMID 39389953, 2024). "Ifitm6+, Hcar2+, Retnla+, Spp1+, C1qb+, and Fscn1+ macrophages mainly existed in tumor tissues." (PMID 36718369, 2023). "As a whole, strong evidence support that HCAR2 in the colon, acts as a tumor suppressor." (PMID 33113952, 2020).
cancer (22 papers, 2011 to 2025). A tumor composed of atypical neoplastic, often pleomorphic cells that invade other tissues. "Similar findings were observed in human carcinoma cells, where HCAR2 activation by niacin induced intracellular Ca2+ release; this effect was abolished by a pretreatment with a G-protein coupled receptor inhibitor—indicating a Gi-dependent mechanism." (PMID 38444010, 2024). "BHB supplementation reduced proliferation of colonic crypt cells and inhibited intestinal tumor growth through HCAR2 activation and induction of transcriptional regulator Hopx, thereby altering gene expression and inhibiting cancer cell proliferation." (PMID 36432618, 2022). "This suggests that circulating BHB produced during fasting or a KD exerts a cancer-preventive effect through HCAR2 activation." (PMID 36432618, 2022). "BHB can activate the cell surface G-coupled receptor HCAR2 (or GPR109A) or can be imported in cancer cells via monocarboxylate transporters (MCT) 1 and 2, frequently over-expressed in cancer." (PMID 39941833, 2025). "HCAR2 and HCAR3 are activated by intermediates of central metabolic processes that are often differentially regulated in cancer cells." (PMID 33113952, 2020). "Hydroxycarboxylic acid receptor 2 (HCAR2), a G protein-coupled receptor for nicotinic acid, has been reported to suppress mammary oncogenesis in mice by inhibiting cancer cell survival." (PMID 32732875, 2020). "A novel theoretical foundation for cancer management against GC is the restoration of intestinal microbial butyrate, which increases CD8+ T-cell cytotoxicity through hydroxycarboxylic acid receptor 2 (HCA2), also known as GPR109A/HOP homeobox (HOPX) and inhibits GC carcinogenesis." (PMID 38730659, 2024).
infection (7 papers, 2018 to 2025). The state of being infected such as from the introduction of a foreign agent such as serum, vaccine, antigenic substance or organism. "Our results identified the infection-mediated upregulation of genes encoding lipid droplet-associated molecules, including anti-lipolytic HCAR2, perilipin -2 and -3, which regulate lipid droplet formation and degradation and HILPDA." (PMID 35531332, 2022). "In conclusion, this study highlights the critical role of HCAR2 in S. aureus infection of the mammary gland and provides a theoretical basis for identifying potential therapeutic targets for such infections." (PMID 39792800, 2025). "However, after infection, HCAR2−/− mice exhibited significantly more pronounced redness and swelling in the mammary glands compared to the NT group, along with an increased number of necrotic foci within the acini." (PMID 39792800, 2025).
metabolic disorders (5 papers, 2022 to 2026). "The hydroxycarboxylic acid receptors HCAR2 and HCAR3 are key targets for treating metabolic disorders, but the structural and ligand-binding properties of HCAR3 remain less understood." (PMID 41359625, 2025). "BHB is also the ligand of two cell surface G-protein-coupled receptors, hydroxycarboxylic acid receptor 2 (HCAR2), also called GPR109A, and free fatty acid receptor (FFAR), which both were thought to play important roles in metabolism and metabolic diseases." (PMID 35784364, 2022).
neurodegenerative disease (4 papers, 2020 to 2021). A disorder of the central nervous system characterized by gradual and progressive loss of neural tissue and neurologic function. "Consequently, indeed, EKSs-generated ketosis (βHB) can alleviate or delay development of neurodegenerative diseases, and improve learning and memory dysfunctions likely through different βHB/HCAR2/AMPK-modulated downstream signaling pathways." (PMID 34206738, 2021). "Thus, ketosis may also improve symptoms of neurodegenerative diseases, motor, learning and memory dysfunctions through anti-inflammatory and anti-oxidative effects via HCAR2." (PMID 34206738, 2021).
cardiovascular disease (3 papers, 2015 to 2023). "Of particular interest, HCAR2 recognizes 3-HB and butyrate and represents a potential drug target for cardiovascular disease and neurogenic inflammatory diseases." (PMID 37993467, 2023). "Importantly, HCAR2 stands as a potential therapeutic target for neuroimmune disorders, cardiovascular diseases and cancers." (PMID 37993467, 2023).
neurological diseases (3 papers, 2019 to 2025). "GPR109A (also known as acid receptor 2 (HCAR2)) plays a critical role in neuroinflammation related to neurological diseases (Taing, Chen, and Weng 2023)." (PMID 39510547, 2025).
HCAR2 also shares sentences with these, for which no sentence is quoted: diabetes (7 papers); inflammatory bowel disease (7); Hypertension (5); Hyperglycemia (4); type 2 diabetic (4); depression (3); enteritis (3); inflammation (3); lupus (3); psoriasis (3); Anxiety (2); Cognitive impairment (2); Crohn disease (2); glioblastoma (2); infectious disease (2); periodontitis (2); pneumonia (2); retinal diseases (2); retinal disorder (2); ulcerative colitis (2); acute pancreatitis (1); acute promyelocytic leukemia (1); alcohol dependence (1); alcoholic fatty liver disease (1); allergic asthma (1); amyotrophic lateral sclerosis (1); asthma (1); Autoimmunity (1); bacterial sepsis (1); breast tumor (1).
A further 44 diseases each share a sentence with HCAR2 in 1 paper.